HOXA-AS2 (HOXA cluster antisense RNA 2)
Diseases named in the same sentence as HOXA-AS2 in open-access papers (continued):
Sharing a sentence is not in itself a finding about the gene and the disease.
cancer (25 papers, 2015 to 2024). A tumor composed of atypical neoplastic, often pleomorphic cells that invade other tissues. "Based on the prior studies that HOXA‐AS2 is implicated in inflammation‐linked cancers, we suggested that HOXA‐AS2 regulates the osteogenic differentiation via mediating NF‐κB activity." (PMID 30536618, 2019). "Additionally, HOXA-AS2 is implicated in the development and progression of various other cancers, including CC, papillary thyroid cancer, type I endometrial carcinoma, NPC, osteosarcoma, NSCLC, bladder cancer (BCa), and thoracic aortic aneurysm." (PMID 38311789, 2024). "Similarly, the high level of expression of HOXA-AS2 is associated with a poor prognosis and the clinicopathological characteristics of cancer patients." (PMID 39409111, 2024). "Studies have shown that high expression of HOXA-AS2 may be associated with various biological processes in malignant tumors, such as apoptosis, invasion, migration, and proliferation." (PMID 34511122, 2021). "Studies have shown that the high expression of HOXA-AS2 may be related to various biological processes of malignant tumors, such as apoptosis, invasion, migration, proliferation, and so on38–41, to be associated with that HOXA-AS2 is highly expressed in AML tissues and cell lines." (PMID 33268767, 2020). "According to reports, long non-coding RNA HOXA cluster antisense RNA 2 (HOXA-AS2) acts as an oncogene in a variety of cancers." (PMID 39170516, 2024). "In cancer, HOXA-AS2/3 is frequently overexpressed in several types of cancer, such as CC, GBM, GC, NSCLC, and OSCC." (PMID 38311789, 2024). "Some studies indicated that the expression of HOXA-AS2 was strikingly upregulated in many types of cancers, such as in non-small cell lung cancer, bladder cancer and pancreatic cancer." (PMID 36528556, 2022). "The role of HOXA-AS2 in malignant tumor development has attracted increasing research interest in recent years." (PMID 32760226, 2020). "HOXA cluster antisense RNA2 (HOXA-AS2), a long-chain non-coding RNA, plays an important role in the behavior of various malignant tumors." (PMID 32760226, 2020). "To recognize the modulatory pattern of HOXA-AS2 in PCa, we screened on starBase website (selecting ten cancer types in pan-cancer)." (PMID 32519740, 2020). "The long non-coding RNA (lncRNA) HOXA cluster antisense RNA2 (HOXA-AS2) has recently been shown to be dysregulated and involved in the progression of several cancers." (PMID 28545023, 2017). "Moreover, multiple studies have demonstrated the tumorigenic role of HOXA-AS2/3 in various cancers, including CRC, gallbladder carcinoma (GBC), GC, HCC, pancreatic cancer (PC), malignant glioma, and others." (PMID 38311789, 2024). "This isoform was included in the isoforms analyzed in the first studies on HOXA-AS2 in cancer." (PMID 35563134, 2022). "Long non-coding RNA HOXA-AS2 (lncRNA HOXA-AS2) have been extensively studied in various cancers." (PMID 36528556, 2022). "Furthermore, HOXA-AS2 was found to be upregulated and to exert the pro-oncogenic function in cancer processes." (PMID 33430870, 2021). "HOXA-AS2 levels were significantly higher in cancer tissues than in normal tissues." (PMID 32760226, 2020). "Next, we analyzed the expression levels of HOXA-AS2 in other types of cancers from GEO." (PMID 26384350, 2015). "Interestingly, HOTAIRM1 and HOXA-AS2 showed positive correlation with the other 16 HOXATs, suggesting that they possibly exert a regulatory effect on all the other 16 HOXATs and may be critical factors in cancer development." (PMID 34805277, 2021). "Unlike the well-established role of HOXA-AS2 in many cancer development progressions, only few demonstrations were concerning the function of miR-2116-3p in cancer process." (PMID 35387643, 2022).
cancer (continued). "In this study, we ascertained that the expression of HOXA-AS2 was upregulated in GC tissues, while significantly downregulated or revealed no expressional difference in other common types of cancer tissues, suggesting that HOXA-AS2 may be an independent clinical marker in GC prognosis and therapy." (PMID 26384350, 2015).
tumor (17 papers, 2015 to 2024). "Conversely, high expression of HOXA-AS2 is associated with larger tumor size, advanced TNM stages, and shorter OS." (PMID 38311789, 2024). "Accumulating evidence suggests that HOXA-AS2 acts as a miRNA sponge to facilitate tumor progression by regulating gene expression." (PMID 38311789, 2024). "In our present study, we as well observed that remarkable enrichment of HOXA-AS2 was not only found in GBM tumor tissues but also in the GBM cell lines." (PMID 35387643, 2022). "The tumor weight of the HOXA-AS2 knockout group was significantly lower than that of the control group." (PMID 33268767, 2020). "Upregulated HOXA-AS2 expression is closely related to increased tumor size, advanced TNM stage and lymph node metastasis in the CRC patients, implying that HOXA-AS2 is tightly associated with tumorigenesis and CRC progression." (PMID 28112720, 2017). "Furthermore, in OSCC, HOXA-AS2 promotes tumor progression by modulating CDK8 and SNX5, while suppressing miR-567 and miR-520c-3p, respectively." (PMID 38311789, 2024). "Hematoxylin–eosin (HE) staining showed that silencing the expression of LNC HOXA-AS2 could destroy the tumor tissue structure." (PMID 33430870, 2021). "By analyzing the clinical characteristics of OSCC patients, we found that the expression of HOXA-AS2 is positively correlated with the TNM stage, but negatively correlated with the degree of differentiation of tumor tissues of OSCC patients." (PMID 36528556, 2022). "HOXA-AS2 inhibits the expression of P21, PLK3, and DDZT3 by binding to EZH2, promotes the proliferation of and inhibites the apoptosis of tumor cells." (PMID 32760226, 2020). "In addition, many famous lncRNAs have been found to involve in gastric tumorigenesis and progression, such as HOTAIR, H19, MEG3, HOXAAS2 and KRT7-AS, also have functions in another type of tumor." (PMID 27637083, 2016).
infection (1 paper, 2024). The state of being infected such as from the introduction of a foreign agent such as serum, vaccine, antigenic substance or organism. "We conducted experiments using the HepG2‐NTCP and PHH models of HBV natural infection to investigate the role of HOXA‐AS2 in HBV replication." (PMID 38647380, 2024).
vascular disorder (1 paper, 2024). A general term used to describe any disease affecting blood vessels]. "Additionally, HOXA-AS2/3 has been implicated in the progression of various diseases, including vascular disorders and inflammation." (PMID 38311789, 2024).
HOXA-AS2 also shares sentences with these, for which no sentence is quoted: lung carcinoma (5 papers); colorectal cancer (4); pancreatic cancer (4); acute lymphoblastic leukaemia (2); liver cancer (2); osteosarcoma (2); prostate carcinoma (2); acute kidney injury (1); bipolar disorder (1); brain cancer (1); cervical cancer (1); Cholecystitis (1); esophagus cancer (1); hepatoblastoma (1); Hodgkin's disease (1); inflammation (1); intestinal cancer (1).